TPO (thyroid peroxidase)
Diseases named in the same sentence as TPO in open-access papers (continued):
Sharing a sentence is not in itself a finding about the gene and the disease.
sensorineural deafness (1 paper, 2021). "Furthermore, TPO mutations have been reported to be associated with sensorineural deafness in humans as well as in animal models, indicating that the TPO enzyme itself may have a role in the development of the auditory system." (PMID 34501348, 2021).
skin changes (1 paper, 2024). "While VLS symptoms might manifest earlier due to localized skin changes, the immune response against thyroid-specific antigens (like thyroglobulin and thyroid peroxidase) might take longer to develop and become detectable." (PMID 38397367, 2024).
synthesis (1 paper, 2025). "Some studies from other countries report that variants in the TPO or TG gene are the most common cause of synthesis disorders, possibly linked to racial and regional variations." (PMID 41334443, 2025).
TAFRO syndrome (1 paper, 2018). "Non-Japanese cases of TAFRO syndrome with positive autoantibodies, including anti-thyroid peroxidase antibody and anti-cardiolipin antibody, have been reported." (PMID 34171004, 2018).
thymoma (1 paper, 2016). A neoplasm arising from the epithelial cells of the thymus. "In a recent study, 16% of 114 EOMG, 9% of 44 LOMG, and 17% of 110 thymoma‐MG patients had antibodies against TPO or TG." (PMID 27781146, 2016). "In thymoma‐MG, anti‐TPO and anti‐TG antibodies were present in 11.1% females and 8.3% males (p = ns)." (PMID 27781146, 2016).
Thyroid adenoma (1 paper, 2015). The presence of a adenoma of the thyroid gland. "FTC showed decreased TPO immunostaining, both in intensity and percentage, when compared to hyperplasia and, to a lesser extent, thyroid adenoma." (PMID 26300979, 2015).
tuberculosis (1 paper, 2015). A chronic, recurrent infection caused by the bacterium Mycobacterium tuberculosis. "Anti-TPO antibody titers, baseline CD4 counts, and history of tuberculosis were the best predictors of subclinical hypothyroidism in HIV infected patients in our study." (PMID 26798547, 2015).
vestibular disorder (1 paper, 2024). Pathological processes of the vestibular labyrinth which contains part of the balancing apparatus. "In 2009, Papi had already noted elevated levels of anti-thyroid peroxidase (anti-TPO), anti-thyroglobulin, and thyroid-stimulating hormone receptor antibodies in a group with vestibular disorders compared with the healthy group." (PMID 38398412, 2024).
viral hepatitis (1 paper, 2023). An acute or chronic inflammation of the liver parenchyma caused by viruses. "When predisposing factors are removed, TPO-RAs may achieve better efficacy in viral hepatitis-related ITP than in primary ITP." (PMID 37635907, 2023).
X-linked agammaglobulinemia (1 paper, 2023). X-linked agammaglobulinemia (XLA) is a clinically variable form of isolated agammaglobulinemia, an inherited immunodeficiency disorder (see this term), and is characterized in affected males by recurrent bacterial infections during infancy. "One individual with X-linked agammaglobulinemia had positive anti-TPO antibodies, but this result should be considered with caution since this particular patient was undergoing IRT." (PMID 37270495, 2023).
tumor (81 papers, 1997 to 2026). "In the subgroup with high TPO antibody, age, calcification, tumor size, laterality, and capsule invasion were the risk factors (p < 0.05)." (PMID 40496557, 2025). "In these mice, the loss of Mettl3 accelerated dedifferentiation and tumor progression compared to TPO-Cre/Mettl3fl/fl/BrafV600E mice." (PMID 39874138, 2025). "The study demonstrated that the loss of miR-31 reduced tumor penetrance, which was nearly 100% in the TPO-CreERT2/BrafCA mice, and the tumors that did form grew more slowly." (PMID 39874138, 2025). "We detected that TPO expression depends on tumor size while being weakly associated with extrathyroidal invasion (p = 0.01) and a high/low recurrence risk (p = 0.02)." (PMID 39000197, 2024). "Thyroglobulin (TG) and thyroid peroxidase (TPO) expression was found to be significantly decreased in tumors, and the lowest level of TPO expression occurred in a tumor harboring both the p.A67GTTF-2 variant and a RET/PTC3 rearrangement." (PMID 22481925, 2012). "Eight variables (sex, age, number of foci, maximum tumor diameter on ultrasound, calcification, capsule, lymph node status on ultrasound, and thyroid peroxidase (TPO) antibody level) significantly associated with risk stratification were included in the predictive model." (PMID 36277684, 2022). "Additionally, we observed statistically significant differences in TPO mRNA expression in association with the tumor grade." (PMID 28575127, 2017). "Nevertheless, TPO may be useful, together with other markers, in confirming or ruling out benign diseases except for low-risk carcinomas such as MIFC." (PMID 26300979, 2015). "However, in our study the risk of VE in ITP patients with a history of previous neoplasia while on TPO-RA was disproportional (more than 40-fold increased risk in elderly patients), suggesting a novel association of these variables with VE in elderly ITP patients under TPO-RA therapy." (PMID 31723222, 2019). "In both ATC lines, SW1736 and 8505c, the treatments resulted in significantly higher expression of TPO compared to non-tumor Nthy-ori 3-1 control cells." (PMID 41463503, 2025). "The proliferation of myeloid tumour cells via TPO-RAs occurs through the stimulatory action of the TPO receptor on the surface of the bone marrow cells." (PMID 39342544, 2024). "In comparison with those of control diluent-treated mice, tumor number and size were increased in TPO-treated mice." (PMID 37064877, 2023). "Conversely, the platelet adhesion inhibitor clopidogrel reduced tumor volumes and weights in wild-type mice treated with TPO." (PMID 37064877, 2023). "The expression level of TPO in PTC tissues correlated with tumor lymph node metastasis and recurrence." (PMID 37407700, 2023). "The strengths of the subcutaneous tumor models coupled with the rapidly penetrant phenotype of our de novo BrafV600E+/−/Pten+/−/TPO-Cre murine model led us to develop a syngeneic tumor model of PTC." (PMID 36765847, 2023). "Paired plots were used to show the difference in TPO expression between normal and tumor samples from the same patient and showed a significant difference (P < 0.001)." (PMID 37407700, 2023). "To further verify the role of PSGL-1 in platelet-induced tumor growth, we established MC-38-bearing mice in the presence of TPO or control diluent and treated these mice with an isotype control Ab or anti-PSGL-1 Ab." (PMID 37064877, 2023). "Mutational analysis and NIS staining failed in one primary tumour sample, TSHR and pendrin staining was inconclusive in one primary tumour sample each, and TPO was inconclusive in one primary tumour and in one lymph node metastasis sample." (PMID 37352166, 2023). "The current work indeed found variable expression of TPO, but our results also suggest that TPO can serve as a marker for the degree of iodine avidity in tumour tissue." (PMID 37352166, 2023).
tumor (continued). "TPO-RA was injected subcutaneously (s.c.)at a dose of 10 μg/kg weekly starting one week before cancer cell injection and continued for 4–6 weeks until tumor-bearing mice became moribund." (PMID 35626102, 2022). "Most HT PTCs were associated with female sex, younger age, smaller tumor size, better TNM stage and elevated TSH, TPO-Ab, and Tg-Ab levels." (PMID 34986823, 2022). "Labeling for synaptophysin and TPO was weak and only a few tumor cells showed immunopositivity for synaptophysin." (PMID 35681825, 2022). "On the other hand, an increase in platelet counts in tumor-bearing mice using TPO-RA increased the expression of PD-L1 in tumors as compared to controls (TPO-RA = 17.2 ± 2.6%)." (PMID 35626102, 2022). "Univariate analysis revealed significant differences in sex, age, nodular composition, number of foci, multifocality, maximum tumor diameter on ultrasound, calcification, capsule, ultrasound-reported lymph node status, and TPO antibody level (P < 0.05)." (PMID 36277684, 2022). "In sum, HrasG12V/Pten−/−/TPO-Cre cell lines represent valuable models for in vivo investigation and allow for studying tumor-immune interactions in immunocompetent hosts." (PMID 33806425, 2021). "Of the cytokines analysed, nine (CD30L, CCL11, CCL24, IGFBP5, IL-4, IL-13, MIP-3ß, CXCL4 and TPO) were significantly more abundant in 4T1 primary tumours than in 67NR primary tumours (Fig. 4aiii)." (PMID 33795809, 2021). "The current tumour marker serum TG takes at least 4 weeks for complete clearance whereas levels of TPO cfRNA changes as early as 1 day after treatment." (PMID 34512731, 2021). "We have previously reported that the HrasG12V/Pten−/−/TPO-Cre de novo model demonstrated extensive CD45+ immune cell recruitment to the tumor microenvironment." (PMID 33806425, 2021). "The strengths of the subcutaneous tumor model coupled with the long latency of our de novo HrasG12V/Pten−/−/TPO-Cre murine model led us to develop a syngeneic tumor model of FTC." (PMID 33806425, 2021). "These 7 variables were as follows: age, suspected LNs, tumor size, microcalcification, irregular shape, TPO-Ab and TSH." (PMID 33193092, 2020). "The variables were arranged in order of mean ranking: suspected LNs, tumor size, age, microcalcification, gender, TPO-Ab, TSH, irregular shape, hypoechogenicity, and capsular invasion." (PMID 33193092, 2020). "Based on multivariate analysis and feature selection, young age, male sex, low serum thyroid peroxidase antibody and US features such as suspected lymph nodes, microcalcification and tumor size > 1.1 cm were the most contributing predictors for CLNM." (PMID 33193092, 2020). "VE on TPO-RA was related to previous neoplasia in patients over 65 years (50% vs. 2.2%, P < 0.001), and to previous splenectomy in younger patients (100% vs. 33%, P = 0.001)." (PMID 31723222, 2019). "Patients with malignancies tested positive for anti-thyroglobulin antibody (TGAb) and anti-thyroid peroxidase antibody (TPOAb) more frequently than those with benign nodules (TGAb, 30.3% vs. 15.0%, p < 0.001; TPOAb, 25.6% vs. 18.0%, p = 0.028)." (PMID 29514621, 2018). "In particular, TPO mRNA and protein have been found to be weakly but clearly expressed in BC tissues, peri-tumor tissues and in fat depots, and although they lack their functional activity, they maintain their antigenic role and can trigger B lymphocytes." (PMID 28273204, 2017). "Although the TPO immunostain for this patient's tumor cells was positive in a few single cells, the vast majority of cells showed negative staining." (PMID 27082575, 2016). "PTC tumours showed underexpression of thyroid function-related proteins TPO, DEHAL1 and thyroglobulin (TG), consistent with the de-differentiation of cellular function." (PMID 27025787, 2016). "The relationship between TPO expression and disease was statistically significant (p <0.001) and decreased with tumor dedifferentiation extent." (PMID 26300979, 2015).
tumor (continued). "Paired analysis of tumor and corresponding normal thyroid samples (possible in 7 cases) revealed a significant decrease (P < 0.0001) in TPO and TG expression among the tumor group, reinforcing previous results." (PMID 22481925, 2012). "This is the matter of our present investigations, with the engineering of CD16/anti-TPO bi-specific aAbs able to physically cross-link immune and tumour cells and thereby to improve cytotoxic activity." (PMID 20145622, 2010). "Age, gender, thyroid peroxidase antibody status, tumor diameter, tumor location, multifocal lesions, capsular invasion, calcification, aspect ratio ≥1, irregular morphology, and tumor diameter ≥1 cm strongly correlated with CLNM in patients with PTC combined with HT." (PMID 41538661, 2026). "TPO, essential for organification of iodide, was markedly downregulated in tumor tissues." (PMID 40746809, 2025). "At the molecular level, we demonstrated that the overexpression of GP73 in HCC cells could promote the secretion of the pro-angiogenic factors CXCL5, MCP-1, and TPO, which are directly correlated with vasculature development during tumor progression." (PMID 38939041, 2024). "This enabled a unique evaluation of the iodine avidity in primary tumour tissue, resected lymph node metastases, and comparison of avidity to the expression of iodine-transport related proteins (NIS, TPO, TSHR and pendrin), as well as mutations in the TERT promoter and codon V600 of the BRAF gene." (PMID 37352166, 2023). "The multivariate regression showed that a model using expression of TPO and NIS, mutation status of the TERT promoter, high-risk histology (tall cell PTC, PDTC and DHGTC) and tumour tissue localisation (primary tumour/lymph node) performed very well in predicting iodine avidity." (PMID 37352166, 2023). "We then explored the expression of TPO at different tumor stages." (PMID 37407700, 2023). "Scatter plots show the difference in TPO expression between normal and tumor samples (P < 0.001)." (PMID 37407700, 2023). "We sought to determine whether subcutaneous tumors were able to recruit a tumor microenvironment similar to the observed in BrafV600E+/−/Pten+/−/TPO-Cre de novo tumors in the thyroid." (PMID 36765847, 2023). "At the same time, the effect of lithium ascorbate was more pronounced and stable: a statistically significant effect of this drug was noted from day 10 and throughout the entire observation period while the TPO index of tumor growth inhibition was at a fairly high level (30–40%)." (PMID 35408651, 2022). "This study analyzes the immunohistochemical expression of TPO (using MoAb-47) in both benign and malignant lesions to establish the relationship between TPO expression, histological type, differentiation degree, and tumor growth." (PMID 26300979, 2015). "In multivariate analysis with adjusting the clinical factors that included age, tumour size, and anti-TPO, the subjects with preoperative Tg greater than 19.4 ng/mL exhibited an increased risk of detectable sTg 6–12 months after RAI ablation (OR: 2.604, 95% CI: 1.339 to 5.062, P = 0.005)." (PMID 25649811, 2015). "Progress has to be made in improving anti-tumour capacities of these anti-TPO recombinant aAbs." (PMID 20145622, 2010). "In addition, in the AOM/DSS-induced CRC model, tumor incidence was 100% in TPO-treated mice." (PMID 37064877, 2023). "Based on the differences in disease latency and tumor penetrance, we hypothesized that HrasG12V/Pten−/−/TPO-Cre cell lines secreted molecules that could be responsible for altering the tumor microenvironment at the cellular level, particularly in regard to immune cell recruitment." (PMID 33806425, 2021). "It has been observed that chronic TSH stimulation, which occurs after the induction of hypothyroidism to raise endogenous TSH, does not alter TSH-R levels and could lead not only to the increased expression of NIS, TG and TPO, but also to an increase in the proliferation and growth of tumor cells." (PMID 33673669, 2021).
tumor (continued). "Several candidate blood biomarkers include serum lactate dehydrogenase (LDH) levels, serum thyroid peroxidase antibody (A-TPO), serum T3 (FT3), serum cytokines, blood cell ratios, serum tumor markers and immune-cell subsets." (PMID 41451213, 2025). "Quantitative analysis demonstrated that NIS, PAX8, NKX2.1, TG, TPO and Hhex levels were significantly decreased upon METTL3 deletion, which suggests that METTL3 promotes TC dedifferentiation and performs a tumour suppressor role." (PMID 38993572, 2024). "By crossing mPTC mice with Rosa26‐mTmG reporter line (mPTCGFP), the TPO‐Cre positive and BRAFV600E‐transformed tumour cells were labelled as GFP+ cells." (PMID 38797942, 2024). "The results showed that the expression of IPCEF1, TFF3, GLT8D2, TPO and DIO1 were downregulated in the tumor group and DPP4, LRP4, CDH3, KCNJ2, CLDN1, GABRB2, FN1 were upregulated in the tumor group." (PMID 39513122, 2024). "The longest tumour diameter, central and lateral LNM and TSH, TG-Ab, TPO-Ab, and Tg levels differed significantly among the groups." (PMID 37884592, 2023). "In addition, quantitative imaging analysis revealed enhanced infiltration of tumor cells and tumor burden in the high-serine diet group compared with control diet group at week 6, which was reduced in the control group and high-serine diet group after TPO administration." (PMID 37055385, 2023). "Clinical characteristics, including age, sex, longest tumour diameter, lesion site, central and lateral LNM, and TT3, TT4, fT3, fT4, TSH, TG-Ab, TPO-Ab, and Tg levels, were compared among the three groups." (PMID 37884592, 2023). "Quantitative immunohistochemical analysis of tumor xenografts from nude mice showed that TSHR, NIS, TPO, and TG expression were all significantly reduced after overexpression of PC." (PMID 36266265, 2022). "After quality control, 11,390 tumor cells (TG, EPCAM, KRT18, and KRT19) and 6,808 normal cells (TG, TPO) were obtained for subsequent analysis." (PMID 35359404, 2022). "Another study in rat tumor thyroid cells (PC-CI3) found a potentiation of the TSH-induced expression of Tg, TPO and NIS by ghrelin." (PMID 28931076, 2017). "Cells from the tumour (FRTC) secreted Tg in vitro and expressed Tg, thyroid peroxidase (TPO) and thyrotropin (TSH) receptor mRNA." (PMID 9000596, 1997). "The correlation between tumor size and the TPO level was negative and relatively strong: the larger the tumor size, the lower the expression level of the thyroid peroxidase gene." (PMID 39000197, 2024). "We found that anti-CSF1R Ab treatment reduced tumor growth and tumor weight in TPO-treated mice but not in mice in the control group." (PMID 37064877, 2023). "Furthermore, the expression of TPO and TSHR in VDR overexpressed tumors was increased than those in control tumors, indicating that VDR promotes DTC tumor differentiation." (PMID 35099410, 2022). "The correlation analysis of the expression of GSTA2 and the identified ROS-associated genes using the LIHC database in the GEPIA web server revealed that the expression level of GSTA2 was significantly correlated with ALB, TPO, APOE, MBL2, and FTH1 in the tumor tissues." (PMID 34290233, 2021). "DTC metastatic tumor cells, in comparison with primary tumor cells, experience a considerable reduction in the amount of essential genes necessary for RAI, such as TG, TSH-R, and Duox2, but a relatively low reduction of NIS and TPO genes." (PMID 33673669, 2021). "Moreover, the tumor cells lack immunoreactivity for the thyroid-specific markers TG, TTF-1, and TPO." (PMID 27082575, 2016). "We do not know exactly why TPO is lost or increased according to tumor growth or development, albeit we suspect that differentiation criteria are involved." (PMID 26300979, 2015). "A causal relationship between genetic alterations and loss of functional NIS expression is present: tumor cells harboring BRAFV600E mutation have decreased NIS, TPO, and TSHR gene expression compared to other tumor cells without this mutation." (PMID 25741318, 2015).